CD27 (CD27 molecule)
Diseases named in the same sentence as CD27 in open-access papers (continued):
Sharing a sentence is not in itself a finding about the gene and the disease.
tumor (continued). "To delineate the role of CD27 signaling in CD8 + T cells in tumor immunity, we have developed CD8 + T cell-specific CD27 knockout (CD8Cre-CD27fl) mice by breeding CD8aCre mice with CD27 floxed mice." (PMID 39105866, 2024). "Indeed, a higher tumor burden was associated with higher frequencies of CD27+CD8+ T cells and CD27+CCT T cells, regardless of whether treatment was given." (PMID 37607911, 2023). "Enrichment of T-cell markers (CD3, CD4), macrophage markers (CD68, CD168), immune checkpoints (CD27 and V-domain Ig suppressor of T-cell activation [VISTA]), CD44 and CD45 were seen in the stroma relative to the tumour." (PMID 37835491, 2023). "IMM40H has a dual mechanism of action: inducing cytotoxicity against CD70+ tumor cells via various effector functions (ADCC, ADCP and CDC) and obstructs the proliferation and activation of Tregs by inhibiting CD70/CD27 signaling." (PMID 37849799, 2023). "To date, both agonist anti-CD27 antibodies and soluble forms of CD70 have been used to investigate the effect of enforced CD27 stimulation on T cell responses and anti-tumour activity." (PMID 37965342, 2023). "Activated GC B cell genes like CD83 and CD40 were highly expressed in tumour‐free TDLN, whereas the expression level of immature B cell markers like CD27 was higher in PT." (PMID 37491740, 2023). "We found that several protein biomarkers, most notably panCK, IDO1, CD44, and Ki-67, were expressed at higher levels in responders’ tumor compartments; however, in the stroma, SMA, Fibronectin, CD4, and CD27 were the most differentially expressed." (PMID 37153589, 2023). "Overall, we observed that PBMCs activated in the presence of conditioned media generated from OGJ patient-derived tumour biopsies at time-points post-FLOT and post-CROSS CRT treatment decreased CD27 and increased CD69 expression." (PMID 35986757, 2023). "The results indicated that gene expression of cytotoxic T-cells, CD8 and Gzmb, and other T-cells, CD27 and CD28, were higher in the tumor treated with combination of anti-PD-L1 and Fc-VFD than treated with the single treatment." (PMID 35895109, 2023). "CD27 is not only constitutively expressed on the majority of both CD4+ and CD8+ T cells, but is also highly expressed on the majority of tumor infiltrating lymphocytes (TILs)." (PMID 37545491, 2023). "Arguing in favor of CD27 agonism, CD27 engagement with an agonist mAb downregulated co-inhibitory receptors in vitro, while it led to CTL-mediated tumor rejection in vivo." (PMID 37345056, 2023). "In conclusion, CD27xEGFR is a novel DVD-Ig bsAb targeting CD27 and EGFR, that has the potential to re-activate T cell immunity in EGFR+ carcinomas through its interaction with tumor-reactive and exhausted CD27+CD8+ TILs." (PMID 37545491, 2023). "This analysis showed that the percentage of CD4+ CD27+ cells and IDO+ monocytes remained independent predictors of tumor progression." (PMID 36900156, 2023). "In contrast, memory T-cell markers and costimulation makers, including CD27, CD44, CD45RO, ICOS, and 4-1BB, were lower within the tumor core of liver metastases, indicating decreased immune activity, possibly contributing to decreased lymphocyte infiltration." (PMID 37768208, 2023). "In non-tumor tissues, immune score and the expression of CD28, OX40, CD137, CD27, PD1, TIGIT, and CD39 were significantly higher in patients with recurrence than those without recurrence." (PMID 37313417, 2023). "The transduction of CD27 or CD28, for which expression is lost in senescent cells, enhances the survival and anti-tumor effects of CAR-T cells." (PMID 38136380, 2023). "CD11c+ cell clusters residing away from the tumor boundary seemed to incorporate many immune cell niches in their environment, indicated by the expression of CD3, CD4, CD45, CD56, CD20, and CD27 in CD11c+ distant segments." (PMID 38044986, 2023).
tumor (continued). "CD27 intracellular structural domain-based TROP2-CAR-T cells promoted relatively higher antitumor activity and T cell persistence in a mouse tumor-bearing model." (PMID 37457288, 2023). "In contrast to the CD8 compartment, the amount of CD28- CD27+ TEMRA cells is significantly lower in CMV seronegative healthy donors compared to CMV seropositive healthy donors, while in tumor patients only a tendency of decreased amounts is observed." (PMID 36831183, 2023). "Accordingly, steady-state DCs remain tolerogenic due to Treg-expressed CD27 which impedes CTL priming and favors tumor outgrowth." (PMID 37345056, 2023). "In a preliminary vaccine study, anti-CD27 agonist combined with PD-1 blockade re-enforced CD4+T-cell help and optimized CTL responsiveness for effective tumor elimination." (PMID 37345056, 2023). "The analysis of two independent cohorts of CLL B cells and PBMCs from a total of 97 patients demonstrated that CD5+CD19+CD27+ memory CLL B cells produce and secrete IL10 and TGFβ1, as part of the tumour cell secretome." (PMID 36973425, 2023). "We also observed that S1P treatment in tumor cells inhibited the expression of TAP2, CD27, CD160, and ICOSLG genes, which are important for the immune cell activation needed for antitumor responses." (PMID 35289120, 2022). "Preclinical studies have also suggested that agonistic mAbs targeting CD27 promote CD8+ T‐cell‐dependent tumour rejection and reduce the frequency of Tregs in a murine tumour model." (PMID 36471481, 2022). "Mice that received both CD27 Treg ablation and PD-1 blockade showed enhanced infiltration of CD8+ T cells into the tumor and those cells displayed enhanced functionality." (PMID 34423375, 2022). "The B-cell populations in the tumor were classified into 7 groups, including naïve B cells, IGM+CD27+ memory B cells, IGM+CD27− atypical memory B cells, class-switched memory B cells, plasma cells, germinal center B cells, and CD14+ atypical B cells." (PMID 35514975, 2022). "Multiple B-cell subpopulation markers are unevenly expressed in B cells, such as CD22, CD27, and CD38, suggesting B-cell heterogeneity in the tumor microenvironment." (PMID 35634306, 2022). "Several studies have indicated that the pathway mediated by CD27 and its ligand CD70 was involved in tumor growth and induction of lymphoid apoptosis." (PMID 35677048, 2022). "Typically, LAG-3 and PD-1 expressions were greater in the tumor, while CX3CR1, CXCR3, and CD27 expressions were lower compared to the PB levels." (PMID 35003893, 2022). "Significant differences in the distribution of perineural invasion, radiotherapy, primary tumor site, and HPV status were noted between the CD27 high- and low-expression groups." (PMID 36458007, 2022). "An in vitro investigation of CD70-targeting CAR T-cells found that the administration of the modified T-cells resulted in T-cell activation, CD27 co-stimulation, and recognition and killing of CD70-positive tumor cell lines and primary tumor samples." (PMID 35565190, 2022). "Tumor-infiltrating Bregs in GC consist of three phenotypes: CD19+CD24hiCD38hi transitional cells, CD19+CD24hiCD27+ memory cells, and IL-10 producing CD27+CD10- cells." (PMID 36618354, 2022). "Nonetheless, CD70-CD27 signaling can occur through the presence of CD27 in the TME facilitating immune evasion and tumor progression by distinct mechanisms." (PMID 34991665, 2022). "Specifically, activated Treg cells destroy tumour immunity by enriching a series of costimulatory molecules (such as ICOS, CD27, 41BB, OX40, and GITR) and immune checkpoints (PD-1, CTLA-4, LAG3, and TIGIT) to promote tumour immune evasion." (PMID 36110969, 2022). "In this review, we present the proliferative role of 15 immune checkpoints, including PD1, PD-L1, FGL1, CD155, CD47, SIRPα, CD276, IDO1, SIGLEC-15, TIM3, Galectin-9, CD70, CD27, 4-1BBL, and HVEM, in tumor progression." (PMID 36358792, 2022).
tumor (continued). "These included genes consistent with pro-inflammatory immune responses (CD27, CD28, CD3e, CD8a, ICOS, ICOSLG, Pax5, TBX, GATA3, HLA-A, TNFSF14, GPR146), but also immune suppressive influences in the tumor immune microenvironment (CTLA-4, FoxP3, PD-1)." (PMID 36698398, 2022). "The expression levels of other hub genes CTLA4, CXCL10, CCL5, CCl4, ICAM1, CXCL9, CD27, GZMB, FCGR2A, SELL, IDO1 in SKCM were higher than those in non-tumor skin tissues (P < 0.05), and the results were statistically significant." (PMID 35710862, 2022). "The CD8+ T cells, the inflammation-promoting function, the high immunity score, the activation of CD27, LAG3, and TNFRSF18, played a critical role in the hot tumour." (PMID 35937987, 2022). "Here, we have used a novel mouse model allowing the selective elimination of CD27-expressing Treg cells at a defined point in time to investigate the CD27-CD70 axis in Treg-mediated suppression of steady state DCs and anti-tumor immunity." (PMID 34423375, 2022). "Here, the tumor cells expressed the ligands CD70 and CD80–CD86 that bind to their respective CD27 and CD28 receptors expressed on CD8+ T cells." (PMID 36180422, 2022). "Analysis of the stromal compartment in primary tumor specimens revealed that the expression of NF1 (HR = 0.748, p = 0.025), CD27 (HR = 0.279, p = 0.035), and CD80 (HR = 0.703, p = 0.02) was associated with a better OS." (PMID 35651606, 2022). "We found that the exhausted CD8+ T cells located in the core of the tumor had a higher expression of immune checkpoint molecules, including PDCD1, CTLA4, LAG3, TNFRSF9/CD137, CD27, and HAVCR2." (PMID 34513820, 2021). "A three-gene signature (SLAMF1, CD27, SELL) model related to the tumor microenvironment was constructed to assess patient survival." (PMID 33766042, 2021). "CD27, an emerging ICI, is being tested as adjuvant therapy in phase I/II clinical trials for multiple tumor types with promising results." (PMID 34503105, 2021). "Subsequently, second-generation CARs containing an additional co-stimulatory signaling molecule, such as 4-1BB, CD28, CD27, OX40 or ICOS have been developed to stimulate an endogenous immune response against tumor cells via epitope spreading." (PMID 33442419, 2021). "CD27 is a new generation of ICI and is being tested as adjuvant therapy in phase I/II clinical trials for multiple tumor types with promising results." (PMID 34503105, 2021). "CD27, a member of the tumor necrosis factor receptor family, is present in CD4, CD8 T lymphocytes and NK cells, plays a significant role in tumor immunotherapy." (PMID 33766042, 2021). "Checkpoint blockade, agonistic antibodies to stimulatory molecules (e.g., OX40, CD137, CD27, and GITR) enhance the activation of T-cells and, as a result, boosted anti-tumor T cell responses." (PMID 34267616, 2021). "CD27 agonism alone and with an PD1 checkpoint inhibitor has also been explored as a potential mechanism of increasing the efficacy of tumor-specific peptide vaccines by enhancing CD4+ helper T-cell and CD8+ cytotoxic T-cell response following vaccination." (PMID 34630390, 2021). "In comparison with adjacent and precancerous tissues, we found a significant reduction of CD40+, CD27+, KLRB1+, and CCL5+ B cells (clusters 4, 9, 1, and 3, respectively) and MZB1+, DUSP1+, and CCL3+ plasma cells (clusters 5, 7, and 8) in tumor tissues." (PMID 34185431, 2021). "Altogether, the upregulated expression of Ki67, IFNγ, CD25, and CD27 among the CD8 and CD4 T-cell clusters indicate that the large tumors in the PD-1cKO are highly immunogenic with a potential for tumor regression, evident at later time points." (PMID 34912335, 2021). "Tumor-infiltrating MAIT cells highly expressed CD69, CD103, CD38, and CD39 with lower expression of CD27 and CD49d compared with peripheral MAIT cells." (PMID 33205061, 2020).
tumor (continued). "Nevertheless, the use of CD27 agonists synergized with PD-1 blockade, by boosting cytotoxic CD8+ T cell-based anti-tumor immunity emphasizing the potential of combinatorial agonistic and antagonistic therapeutical approaches." (PMID 32674488, 2020). "CD27 expression is almost exclusively restricted to immune cells in solid tumour types, in contrast to CD70-CD27 co-expression on tumour cells in hematopoietic malignancies." (PMID 31652572, 2019). "They show an activated immune phenotype (CD23+, CD27+, CD80+) and are capable of tumor-specific Ig production." (PMID 31167511, 2019). "Cell line screening showed the enrichment of cancer cells deprived of the expression of CD27, CEACAM1, CTLA4, LRIG1, PDCD1LG2, or TNFRSF18, suggesting their role as tumor suppressor." (PMID 31358815, 2019). "Consistently, the tumor-infiltrating TIM-1+B cells showed increases in the expression levels of CD5, CD27 and CD38 compared to the TIM-1−B cells." (PMID 30526680, 2018). "We defined the differentiation stage of the different lung and tumor T cell subsets by analyzing the surface expression of CD45RA, CD28, CD27, and CCR7." (PMID 30505306, 2018). "Results of comparative in vivo studies of CARs containing these various costimulatory domains demonstrated that both 4-1BB and CD27, members of the TNFR superfamily, enhances T cell anti-tumor activity and persistence." (PMID 29980239, 2018). "In this manuscript, we describe the creation of a novel co-stimulatory HERA molecule that is able to target CD27 and furthermore use HERA-CD27L to demonstrate the powerful immuno-stimulatory and anti-tumor activity of this approach." (PMID 30298117, 2018). "We purified neutrophils from the peritoneal cavity of tumor-bearing Cybb−/− or WT mice and co-cultured them with anti-CD3/CD28-stimulated CD27− γδ T cells." (PMID 29750788, 2018). "Whereas anti-CD27 antibodies, such as Varilumab (CDX-1127), just boost innate and adaptive antitumor responses, anti-CD70 antibodies also target tumor cells inducing direct cell killing." (PMID 29387053, 2017). "Macrophage depletion was also performed using liposomal-encapsulated clodronate, but depletion of macrophages itself impairs BCL1 tumor growth, thus preventing us from assessing the contribution of macrophages to anti-CD20/CD27 therapy." (PMID 29198913, 2017). "A similar strategy uses atezolizumab in combination with varlilumab (an agonistic anti-CD27 mAb), which results in an increase of the CTL response against CD27 ligands expressed on tumor cells (NCT02543645)." (PMID 29312320, 2017). "We also determined that anti-CD19/CD27 CAR and anti-CD19/CD28 CAR were comparable to each other with respect to cytokine release and cytotoxicity against tumor cells." (PMID 27598655, 2016). "The data indicate that decreasing CD8+/CD57+ and CD27− T cell fractions correspond to increasing tumor load in NF1 patients, potentially making these populations useful marker for internal tumor burden." (PMID 27448806, 2016). "In ovarian cancer model, it has been reported that CD27− Vγ6+ cells produced higher IL17 and induce VEGF and Ang-2 in peritoneal exudates of tumor bearing mice after 6 weeks of post-tumor inoculation." (PMID 25699053, 2015). "Subsequently, the phenotype of CD27+ TILs was investigated in serial cuts of CD70+ and CD70− tumor samples." (PMID 25951351, 2015). "In this perspective, chimeric antigen receptor T cells (CD27-CD3ζ) have been reported to kill CD70+ tumor cells and mediate tumor regression in mice." (PMID 25792975, 2015). "ARGX-110, a human CD70-specific monoclonal antibody which is currently undergoing Phase I clinical testing, is a strong antagonist of CD70/CD27 signaling and mediates destruction of CD70-expressing tumor cells through enhanced ADCC." (PMID 25951351, 2015).
tumor (continued). "An alternative therapeutic approach to blocking immunosuppressive checkpoint molecules has been to enhance T-cell activation and anti-tumor response via agonists to co-stimulatory surface receptors, such as 4-1BB, GITR, CD27, and OX40." (PMID 26317902, 2015). "Post-activation NK cells expressed CD27, CD90, CD127, and were low for CD11b suggesting that tumor-induced activation is restricted to an early NK cell subset." (PMID 25101668, 2014). "By investigating the expression of CD11b and CD27 on TINK cells from NSCLC patients, we characterised the maturation status of tumour-infiltrating NK-cell subpopulations." (PMID 23565296, 2013). "We recently showed that the aAPC platform induces numerically similar expansion of TIL compared with REM, and these TIL have a “young” CD27+CD28+ phenotype, are enriched for CD8+ T cells, contain fewer Tregs and are tumor-reactive." (PMID 23402380, 2013). "Ex vivo expansion of TIL with the IL-2-based systems greatly reduces CD27 and CD28 expression, resulting in reduced persistence and subsequent limited anti-tumor activity in vivo." (PMID 23402380, 2013). "These "young" TILs are tumor-reactive, positively skewed in CD8+ lymphocyte composition, CD28 and CD27 expression, and contain fewer FOXP3+ T cells compared to parallel IL-2 cultures." (PMID 21827675, 2011). "In T cells, CD25 ligation provides signals required for optimal anti-tumor activity and CTL persistence in vivo, whereas CD27 regulates T cell survival, and CD62L mediates T cell trafficking." (PMID 17786193, 2007). "Conversely, when monitoring the NK cells expressing CD27 or B220, a slight increase in these cell populations was observed for tumor-bearing mice compared to healthy mice, with a higher trend observed for the GDQ group (p < 0.05) with respect to CD27-positive NK cells." (PMID 41597427, 2026). "Neither CD70 expression (rs = -0.0421, p = 0,713), nor CD27 + cellular density (rs = 0.0165, p = 0.881) show significant correlation with tumor stage, suggesting an expression pattern inherent to the original tumor phenotype." (PMID 40205178, 2025). "In contrast, the tumor-specific cluster C3 appears less differentiated with features typical of CD56brightCD16neg NK cells (NCAM1, CD2, CD27, SELL, CD69) as well as a signature of tissue residency (CD69 and ITGA1) and of TGF-β-induced genes (SMAD7, TGFB1, PMEP1, SKIL)." (PMID 41145419, 2025). "An mRNA based transient NKG2D CAR-NK cells without DAP10 but CD27/28, enhance NK cell tumor responses significantly against various solid tumor cell lines in vitro and demonstrating therapeutic benefits in mice with established colorectal cancer." (PMID 40612946, 2025). "Furthermore, we quantified the tissue expression of CD70’s receptor, CD27 in the TME and its colocalizing expression signals with tumor- stromal and immune cells." (PMID 40205178, 2025). "In our cohort, CD27 expression was restricted to the TME, showing coexpression with vimentin + CAFs, CD3 + T-cells, and a moderate number of CD68 + TAMs in the stroma and tumor nests." (PMID 40205178, 2025). "The percentage of CD27 positive tumor antigen-reactive T cells in 12GM-DC group was significantly higher than that in GFP-DC group, indicating that 12GM-DC culture system enhanced the activation of tumor antigen-reactive T cells in vivo." (PMID 41333469, 2025). "Specifically, it was observed that highly immunogenic tumors had a higher proportion of EMRA CD8+T cells that were negative for CD27/CD28 expression at the tumor site." (PMID 40426949, 2025). "Subsequently, all factors identified from the univariate analysis were included in the multivariate analysis: age, PDCD1/CD27 ratio, PDCD1/TNFSF4 ratio, IDO1/TMIGD2 ratio, IDO1/TNFSF4 ratio, neoadjuvant treatment, initial weight of tumor, ER status, PR status, HER2 status, and TNM stage." (PMID 40061889, 2025).